CD4 (CD4 molecule)
Diseases named in the same sentence as CD4 in open-access papers (continued):
Sharing a sentence is not in itself a finding about the gene and the disease.
tumor (continued). "The results showed that MIR155HG was significantly negative associated with tumor purity, positive correlated with B cells, CD8+ T cells, CD4+ T cells, macrophages, neutrophils and DCs." (PMID 31568700, 2019). "However, the levels of CD4+CD28− and CD8+CD28− cells were significantly lower among TIL in PEF2 and PEF2+Ca-treated mice (average 17–23%) compared to tumor-bearing controls (about 30%)." (PMID 31717542, 2019). "In addition, the number of CD4+ and CD8+ T lymphocytes in tumor tissues from mice in the combination treatment group was also significantly increased, as shown by IHC and WB." (PMID 30778049, 2019). "We showed that the heterogeneous tumor human leukocyte antigen-1 expressions differently affect the magnitude of cytotoxic T-cell infiltration and the distributions of CD20+ B cells and CD4+FOXP3+ regulatory T cells within and outside of T-cell infiltrated tumor areas." (PMID 31166985, 2019). "In addition, a balanced ratio of CD4+ Th cells and CD8+ cytotoxic T cells can positively influence the product regarding tumor eradication." (PMID 31835562, 2019). "The PanTT39 CD4+ TIL clone recognised a mutant peptide derived from the aquaporin (AQP)-like putative transmembrane ion/water channel K7N7A8 protein product, which also induced potent cytotoxicity against the autologous tumour cell line." (PMID 30377343, 2019). "Like in NSCLC patients, chronic COPD-like inflammation associated with a heterogeneous immune cell population characterized by the presence-of neutrophils, the expression of PD-1 in CD8 T cells and the presence of PD-1+, CD4+, and CD8+ cells in the tumor microenvironment." (PMID 31316109, 2019). "In fact, its negative activity has been observed in CD8+ tumor-infiltrating lymphocytes (TILs) and in CD4+ TRegs." (PMID 31641355, 2019). "CD4+CD8αα and CD4+CD8αβ T cell clones were then stimulated for 48 h with anti-CD3/CD28 antibodies and supernatants were harvested to measure levels of antitumor Th1-type cytokines (IFN-γ, TNF-α), as well as of pro-tumor Th2-type cytokines (IL-4, IL-5)." (PMID 30984190, 2019). "In order to separately investigate anti-tumor functions of CD8+ and CD4+ T cells transduced with 19305DP-TCR, we polyclonally activated and retrovirally infected PBMC depleted of CD4+ or CD8+ cells to obtain TCR gene-transduced CD8+ or CD4+ T cells, respectively." (PMID 30626427, 2019). "In addition, the anti-tumour effects of Lm-NP were analysed based on the immune response, showing the mutual participation of both CD4+ and CD8+ T cells, demonstrating a potent anti-tumour immunity triggered by recombinant L. monocytogenes." (PMID 31528208, 2019). "Although in addition to TAM, bone marrow is the origin of several other immune cell types, we already demonstrated that Cav-2 deficient TAMs rather than CD4 and CD8 T cells initiate anti-tumor cascade." (PMID 31831780, 2019). "Both CD4 and CD8 epitopes are considered as important for effective anti-tumor immunity." (PMID 31722672, 2019). "We show that drug synergy is driven by induction, not only of T effector cell activation by α-PD-1, but of a competing TGFβ-driven immunosuppressive program that acts to induce tumor cell EMT and polarization of CD4+ T cells to blunt the response to α-PD-1 therapy." (PMID 30832732, 2019). "Indeed, we observed a substantial decrease in both CD4+ T cell and CD8+ B cell viability after depletion of TIL-Bs from tumor-derived cell suspensions." (PMID 31623665, 2019). "Even more surprising considering their tumor-permissive properties, the CD103−CD11b+ DC subset induces CD4+ T cells to express high TH1- and TH17-family cytokines and transcription factors, including a substantial IFNγ+IL17+ population, which co-expresses IL-10." (PMID 30926808, 2019). "In contrast, the recurrent tumor was NF-κB/p65RelA, but relatively immune-quiet with no detectable CD4, CD8 or PD-1 positive cells." (PMID 31618954, 2019).
tumor (continued). "The activation of both CD4+ and CD8+ T cells in cancer patients following CVA21 treatment suggests the induction of a T cell immune response; however, its relationship to anti-viral and/or anti-tumor immunity is unclear." (PMID 31262361, 2019). "Strikingly, our current study revealed a marked augmentation of CD4+Ki67+ and CD8+Ki67+ T cells in tumor dLN in HPK1 KD mice, further support the positive interplay between CD4+ and CD8+ T cells upon inactivation of HPK1 kinase in tumor bearing mice." (PMID 30913212, 2019). "We reveal excessively activated pp38 MAPK-pMAPKAPK2 signaling expressed by EpCAM+ CD4+ T cells in tumor tissues in CC patients, indicating that the p38 MAPK pathway might be a potential therapeutic target in EpCAM+ CD4+ T cell-rich CC patients." (PMID 31354723, 2019). "CD4+ Th1 and CD8+ T cells have major roles in anti-tumor immunity." (PMID 31491023, 2019). "IL-17 signaling does not impact proliferation or activation of tumor-infiltrating CD4+ and CD8+ T cells." (PMID 31775909, 2019). "Importantly, depletion of B cells led to markedly lower viability of CD4+ and CD8+ T cells in tumor-derived cell cultures." (PMID 31623665, 2019). "Interestingly, the frequency of Treg cells is correlated with the tumor load, and co-culture of CLL cells with CD4+ T cells induces a forkhead box P3+ (FoxP3+) Treg phenotype, indicating that CLL cells induce Treg differentiation." (PMID 31484424, 2019). "The results showed that CD4+/CD8+ T-cell ratio in naloxone group was higher 48 h after the operation, suggesting that low dose naloxone may enhance cellular immunity and anti-tumor effects." (PMID 31856760, 2019). "Additionally, Delta-24-RGD/radiotherapy treatment significantly increased the trafficking of immune cells (CD3, CD4+ and CD8+) to the tumor niche compared with single treatments." (PMID 31036068, 2019). "Vaccination with iPSC-based cancer vaccine also induced CD4+ and CD8+ T cells that could recognize tumor cells in vitro, suggesting the induced immune responses are tumor specific." (PMID 31338094, 2019). "Eftimie and Hamam modeled the non-robustness of tumor cell elimination by macrophages due to the presence of two types of CD4+ T cells." (PMID 32117197, 2019). "Collectively, oxaliplatin depleted Mo‐MDSCs and PMN‐MDSCs in tumor‐bearing mice, analogously to gemcitabine, but it did not significantly affect levels of effector CD4+/CD8+ T cells or Tregs." (PMID 30592157, 2019). "The therapeutic effect was associated with marked distant tumor infiltration with activated CD8+ and CD4+ effector but not with regulatory T cells, and was dependent on CD8+ T cells, NK cells, and type I interferon." (PMID 31480379, 2019). "This study showed increased levels of CD4+ and CD8+ T cells and significant tumor necrosis in treated patients, suggesting that CAR-T cell therapy could be a promising treatment strategy for patients with solid tumors." (PMID 30987642, 2019). "Moreover, LAG3 is known to be expressed on the surface of CD4+ and CD8+ cells, implicating the possibility that the tumor-infiltrating lymphocytes (TILs) within immune-inflamed LUSCs of our study were in a more exhausted state than immune-inflamed LUADs." (PMID 30956762, 2019). "Others demonstrated that patients with tumor recurrence showed significative reduction of CD4+ T cells compared to nonrecurrence patients." (PMID 30941374, 2019). "In patients with primary UM, while circulating anti-tumor CD3–CD56dim NK cells and CD8+ and double-negative CD3+CD56+ NK-T cells decrease, pro-tumoral ICOS+CD4+FoxP3+ Treg cells increase, further supporting a role for Treg in tumor progression." (PMID 31750244, 2019). "Runx3 is a well-established regulator of CD4+ and CD8+ T cells, so we assessed whether miR-301a deletion alters tumor stromal immune responses." (PMID 31122259, 2019). "Growing evidences in the literature indicate that CD4+ T cells have direct roles in anti-tumor and anti-viral responses without contribution of CD8 or B cells." (PMID 31156634, 2019).
tumor (continued). "Additionally, we performed the in vitro suppressive assay using isolated CD4+CD25+ Treg cells from the peripheral blood and tumor tissue of NSCLC patients and isolated CD8+ T cells from the peripheral blood." (PMID 31801611, 2019). "These T-lymphocytes were predominantly CD8+ cytotoxic lymphocytes, whereas CD4+ T-lymphocytes were scarce in the adenocarcinoma, and lymph node metastases, were mainly absent in the bulky tumor." (PMID 30696472, 2019). "Therefore, the induction of tumor immunity by GITR Ab is attributable to both the co-stimulatory activity of GITR on responder CD4+CD25− T cells and to a direct effect on CD4+CD25+ Tregs11–13." (PMID 30944344, 2019). "And HPV-specific CD4+ T cells could release IFN-γ and TNF-α, which had the capacity of synergizing with cisplatin-based therapy to control tumor cells growth." (PMID 31001266, 2019). "We previously identified a WT1 protein-derived 16-mer HLA class II peptide, WT1332 (KRYFKLSHLQMHSRKH), which can elicit WT1332-specific CD4+ T-cell responses, and demonstrated that this WT1332 peptide was endogenously generated from the WT1 protein in WT1-expressing tumor cells." (PMID 30430205, 2019). "Contrarily, flow cytometry examines the total tissue harvested and does not differentiate between tumor-excluded or tumor-infiltrating CD4+ and CD8+ T cells." (PMID 30670061, 2019). "The activation of these T helper, CD4+/CD3+, and CD8+/CD3 + cells may help to inhibit or delay the tumor progression." (PMID 31372176, 2019). "CD4+ T cells are the orchestrators of the immune response and therefore they have great potential to recruit other cells such as CD8+ CTL or natural killer (NK) cells to the site of the tumor." (PMID 30956760, 2019). "Subsequently, antibody therapy increased the CD8+ T-cell:Treg ratio in the tumor without further augmentation from peritumorally administered DR-BMCs, but tritherapy significantly increased the ratio of tumor CD4+ Teffs:Tregs compared to all other groups." (PMID 31747946, 2019). "In the context of dysfunctional CD4+ T helper cells, the “helpless” tumor specific CD8+ T cells could ultimately develop functional deficits with impaired tumor-specific CD8+memory T-cell responses." (PMID 30913212, 2019). "In vitro, MT110 exhibited a potent activity in killing EpCAM-overexpressing tumor cells by redirected unstimulated human peripheral T cells (CD4+ and CD8+).16, 62 MT110 was efficacious in three in vivo models (tumor growth inhibition and elimination of established tumors)." (PMID 31011631, 2019). "Memory CD4 and CD8 T cells could protect the immunized mice from tumor re-challenge for as long as 6–12 months." (PMID 31244823, 2019). "Among the immune and inflammatory cells, CD8+ T cells and CD4 helper T cells 1 (TH1), NK cells, M1 macrophages, dendritic cells work against the tumor while regulatory T cells, M2 macrophages, myeloid derived suppressor cells (MDSC), CD4 helper T cells 2 (TH2) cells promote tumor growth." (PMID 30991694, 2019). "STAT3 inhibition was further shown to induce upregulation of several intracellular signaling molecules that are involved in T-cell and monocyte activation and may be used to promote CD4 and CD8 T cell-mediated tumor elimination." (PMID 31698775, 2019). "NKG2D-specific CART cells could recruit and activate endogenous antigen-specific cytotoxic CD8+ cells and CD4+ Th cells in the tumor site in a CXCR3-dependent manner, leading to improved tumor eradication." (PMID 31835562, 2019). "Furthermore, the knockdown of Hat1 significantly increased tumor infiltration of immune effectors including CD45+CD8+ T cells and CD45+CD4+ T cells, but decreased the infiltration of CD11b+Gr1+ myeloid cells in tumors." (PMID 30709380, 2019). "Regulatory T-cells (Treg, CD3+CD4+CD25+) mediate immune suppression by secreting interleukin (IL-) 10 and transforming growth factor (TGF-) β to provide a helpful tolerogenic environment for tumor development and progression." (PMID 31212819, 2019).
tumor (continued). "However, other subsets of CD4 T cells, particularly regulatory T cells and TFH cells, inhibit tumor immunity, thereby promoting cancer growth." (PMID 31632199, 2019). "Treg cells are characterized by the expression of CD4, CD25, and FOXP3, although they may show phenotypic diversity and functional heterogeneity in different types of tumor and tissues." (PMID 31365790, 2019). "Instead, SM16 treatment causes expansion of a population of CD4+CD25−Foxp3+ Treg-like cells without significantly altering the overall frequency of Treg in lymphoreplete naive and tumor-bearing mice." (PMID 31288845, 2019). "Thus, increasing of the activities of immune cells such as CD3, CD4, CD8, and NK1.1 thereby confer increased the phytochemical constituents efficacy, resulting in impaired tumor metastasis and progression." (PMID 31783838, 2019). "In the context of tumor progression, a report showed that absence of miR-21 reduced the proliferation of both CD4+ and CD8+ cells and their cytokine production, thus accelerating the growth of grafted tumors." (PMID 31710308, 2019). "CD4+ T cells and Treg also predominantly increased in the tumor center, but this was not significant." (PMID 31287991, 2019). "We detected a significant decrease in CD4+ tumor infiltrated cells, without significant changes in CD8+ cells compared with controls, whereas in the spleen, neither CD4+ nor CD8+ showed any changes respect to controls." (PMID 31695610, 2019). "Besides, a clinicopathological study on 64 PCNSL patients shows that the PD-L1 protein is detected in tumor microenvironments than in tumor cells and is correlated with expression of interferon-gamma (IFN-γ) and CD4 with OS16." (PMID 31292525, 2019). "North has shown that one form of experimental chemotherapy, namely the administration of cyclophosphamide, is effective not (only) because it kills tumor cells, but by killing dividing CD4 T cells of a mouse given a lethal tumor challenge." (PMID 31231378, 2019). "The percentage of CD4+ and CD8+ T cells in CD45+ cells was also reduced in the residual tumor." (PMID 31780645, 2019). "Moreover, the PD-L1 counterpart, PD-1, was expressed on the vast majority of tumor-resident CD8+ and CD4+ T cells." (PMID 31694706, 2019). "DCs treated with EVs loaded with chaperone-enriched glioma lysate promoted the proliferation of CD4+ and CD8+ T cells and the activation of anti-tumor CTLs ex vivo, as well as the significant inhibition of tumor growth and prolonged survival of tumor-bearing mice." (PMID 31680949, 2019). "Notably, imiquimod treatment of breast metastases in the skin not only converted them from cold to hot, as demonstrated by a profound infiltration with CD4+ and CD8+ T cells, but also led to tumor regression." (PMID 31481117, 2019). "We further identified an immunosuppressive microenvironment within the tumour, showing increased recruitment of myeloid-derived suppressor cells (MDSCs) rather than regulatory CD4+ T cells (Tregs)." (PMID 31588122, 2019). "Indeed, anti-CD20 therapy led to a long-lasting protection against CD20+ tumor cells in mice by inducing a CD8+ and CD4+ dependent cellular immune response." (PMID 31572357, 2019). "Moreover, co-encapsulation of the invariant NKT cell agonist, together with the TLR 7/8 agonist R848 (Resiquimod) and polyI:C into PLGA nanoparticles enhanced CD4+ and CD8+ mediated anti-tumor responses mainly dependent on DC condition via NKT cells." (PMID 31024545, 2019). "The results showed increased CD4+ T‐cell infiltration in the tumor area than in adjacent noncancerous tissues in Doc‐treated paraffin‐embedded specimens from PCa patients." (PMID 31018021, 2019). "Besides, the frequency of IFN-γ-producing CD4+ T cells and CD8+ T cells in Becn1 knock-down tumor tissue was markedly increased." (PMID 31300052, 2019).
tumor (continued). "Similarly, increased rates of CD4 Tcm in lymph nodes and TIL and CD8 Tem/Teff/Tcm in TIL were observed after the PEF2 and PEF2 + Ca treatments (compared to tumor-free and tumor-bearing untreated control)." (PMID 31717542, 2019). "In addition to its effects on the CD4+/CD8+ ratio, lycopene also increases the number of IFNγ expressing CD8+ T cells in tumor tissues." (PMID 30948928, 2019). "Although CD4+ cells were substantially enriched in all four groups, the percentages of immunosuppressive Tregs in tumours post combined treatment did not significantly decrease." (PMID 31048681, 2019). "CD4+ T cells are critical effectors of anti-tumor immunity, but how tumor cells influence CD4+ T cell effector function is not fully understood." (PMID 31300052, 2019). "Baseline PET imaging of CD4+ and CD8a+ was conducted in the same panel of syngeneic mouse models prior to treatment with Sym021 to evaluate the predictive value of TIL imaging for treatment response across various tumor types." (PMID 31754392, 2019). "Antibody therapy increased CD4+ T-cell (both Teff and Tregs) proliferation compared to untreated mice, however only tumor CD4+ Teffs and not Tregs proliferated even further with tritherapy." (PMID 31747946, 2019). "Our in vitro data also showed that tumor Sdc-1 silencing did not significantly alter the proportion of the Th2 (IL4+CD4+) subset among CD4+ T cells of non-IBC patients under indirect and direct co-culture conditions." (PMID 31145753, 2019). "The increase in the CD4+ T cell population was not significantly different comparing eCPMV-vs PBS-treated tumor-bearing mice." (PMID 30974896, 2019). "In addition, the proportion of immune cell types (B cells, CD4+ T cells, CD8+ T cells, neutrophils, macrophages and dendritic cells) of tumor sample in the TCGA cohort was calculated by TIMER for reverse analysis." (PMID 32047513, 2019). "Flow cytometry analysis showed that VD did not affect the presence of CD4+CD25+CD127low/- T cells in the tumor both in basal and high-fat conditions." (PMID 31244851, 2019). "In addition, tumor-infiltrating T cells, triggering by CCL2 produced by cancer cells, TAMs, and CAFs acquire CD4/CD25 expression and transform to Treg in TME." (PMID 31450710, 2019). "In a murine breast tumor model, DCs loaded with tumor antigens and siRNA against IDO1 decreased the tumor size and the apoptosis of CD4+ and CD8+ T cells, when compared to DCs without IDO1 silencing." (PMID 30658461, 2019). "Here, we have revealed a TRAPs-mediated regulatory mechanism of CD4+ T cells differentiation whereby HSP90α on the surface of TRAPs educate CD4+ T cells via a TLR2–autocrine IL-6 cascade to express IL-10 and IL-21 and engender immune suppression to promote tumor growth and metastasis." (PMID 31300052, 2019). "We did not observe any changes in CD4+ T cell infiltration per milligram of tumor in mice that received class I HER2-DC1 alone or in combination with anti-PD-1 antibody therapy." (PMID 31475002, 2019). "Interestingly, both CD4+ and CD8+ UniCAR armed T cell subpopulations get activated in a TM-dependent and tumor-specific manner." (PMID 31332252, 2019). "The percentage of intratumoral CD4+ T cells was not altered, while a reduction in tumor infiltrating NK cells was noted." (PMID 30315349, 2019). "The authors were able to demonstrate a decrease in tumor growth in vivo, and upon depletion of CD4+ and CD8+ T cells, a lack of tumor cell response, indicating the necessity of a T cell response for anti-tumor effects." (PMID 31847387, 2019). "Consistent with the results obtained in vivo with the EVs-ARG1 in the adoptive transfer model in non-tumor settings, ID8-ARG1 bearing-mice had a significantly reduced percentage of activated CD69-positive CD4+ and CD8+ T-cells in the peritoneal cavity relative to mice bearing control tumor cells." (PMID 31278254, 2019).